CSK (C-terminal Src kinase)
Diseases named in the same sentence as CSK in open-access papers (continued):
Sharing a sentence is not in itself a finding about the gene and the disease.
cancer (continued). "Therefore, we used the designed biosensor to detect the activity of the CSK protein in normal cells and cancer cells and performed a comparative analysis." (PMID 38667199, 2024). "The activity of CSK is detected by the FRET reactions of the biosensors in cancer cells." (PMID 38667199, 2024). "CSK is effective in inhibiting cancer progression, while its downregulation supports tumorigenesis." (PMID 38667199, 2024). "Indeed, many cancer cells express low levels of CSK and elevated activation of SFKs, leading to more invasive cell phenotypes." (PMID 37519303, 2023). "Its pivotal role in cancer cell signaling earmarks CSK as a promising target for cancer therapy." (PMID 38304232, 2023). "In this section, we will delve into the structure and regulation of CSK and examine some specific examples that demonstrate how CSK may regulate cancer progression through integrin/SFK signalling." (PMID 37519303, 2023). "Knockout (KO) mice can be used to show that CSK plays a key role in anti-cancer effects." (PMID 36983027, 2023). "CBP expression is downregulated in several types of cancer cells and may interfere with CSK translocation to the plasma membrane." (PMID 37519303, 2023). "Despite extensive research on SFK oncogenic signalling, the specific role of CSK and its crosstalk with integrins in cancer progression, for example, in mechanosensing, remains unclear." (PMID 37519303, 2023). "Thus, dysfunction of the mechanisms that ensure proper CSK function in a normal cell, promotes cancer." (PMID 36578781, 2022). "Roles of CSK in metastasis of human cancer cells have also been suggested." (PMID 23593342, 2013). "Furthermore, the ability of CSK to control focal adhesion protein phosphorylation may have a key impact in cancer progression and metastasis." (PMID 37519303, 2023). "The relevance of CBP enabling efficient inactivation of SFKs by CSK has also been proven to be crucial in preventing tumorigenesis and controlling GFR signalling in cancer." (PMID 37519303, 2023). "CSK can define integrin-SFK-mediated cell adhesion signalling, which can also impact the metastatic potential of cancer cells." (PMID 37519303, 2023). "Abnormal functioning of CSK and SFK activation can lead to diseases such as cancer, cardiovascular and neurological manifestations." (PMID 36578781, 2022). "This threshold was met in at least one cancer cell line by 39 (52%) kinases and by 23 kinases in at least two cell lines, including CDK5, CSK, LYN, RSK2 and YES." (PMID 22277058, 2012). "Immediate effects of siRNA on SK-BR-3 growth on the Test Cancer Biochip were observed at day 2 for ERBB2, ESR2, CSK, CTSL2, and BRAF siRNAs." (PMID 23049944, 2012). "In summary, the difference in CSK activity in cancer cells and non-cancer cells is not obvious, and the relation between the CSK protein and cancer development needs to be further explored." (PMID 38667199, 2024). "The biosensor did not detect obvious changes in CSK activity between metastatic cancer cells and normal ones." (PMID 38667199, 2024). "In summary, CSK plays a crucial role in defining integrin-SFK-mediated cell adhesion signalling, which may significantly impact the metastatic potential of cancer cells." (PMID 37519303, 2023). "Consequently, CSK may play a pivotal role in tumour progression and suppression by inhibiting SFK oncogenic effects in several cancer types." (PMID 37519303, 2023). "The SFKs include the non-receptor tyrosine kinase C-terminal Src kinase (CSK), which plays a pivotal role in tumour progression and suppression by inhibiting SFK oncogenic effects in several cancer types." (PMID 37519303, 2023). "Additionally, another study on ER-positive breast cancer found that in cases of endocrine therapy resistance, reduced CSK leads to enhanced PAK2 activity and subsequent non-estrogen-dependent cancer growth." (PMID 38304232, 2023).
tumor (33 papers, 2004 to 2025). "Authors here identify a pathway in T cells that leads to increased activity of C-terminal Src kinase, a negative regulator of T cell activity, thus disabling tumour infiltrating T cells and causing immune therapy resistance." (PMID 36376335, 2022). "Overall, the in vivo drug treatment study further suggests that synergistically inhibiting PI3K and MAPK pathways can significantly inhibit tumor growth in those lapatinib resistant tumors with loss of function mutations of CSK or PTEN." (PMID 34399705, 2021). "A down-regulation of CSK, which acts as a tumor suppressor gene, has previously been associated with colon cancer." (PMID 28874816, 2017). "SIN3A and CSK both play roles in tumor suppression and their deletion may lead to an increased predisposition to and risk of neoplasia in this patient population." (PMID 22216833, 2012). "The dual effect of CSK in both tumor suppression and inducing endocrine treatment resistance positions it as a notable target for research." (PMID 38304232, 2023). "Mice deficient in the Tnk2 gene encoding Ack1, are characterized by diminished CSK Y18-phosphorylation and spontaneous activation of CD8+ and CD4+ T cells, resulting in inhibited growth of transplanted ICB-resistant tumours." (PMID 36376335, 2022). "For instance, in B cell lymphoma, use of CSK inhibitor could facilitate the T cell response against tumor and suppress the growth of transformed B cells by blocking their downstream PI3K signaling." (PMID 37397251, 2023). "Results from both genetic and pharmacological intervention of Ack1 indicate that the ACK1/pY18/CSK axis is involved in dampening T-cell priming and T-cell trafficking to the tumor microenvironment partially responsible for the resistance to the immune checkpoint blockade (ICB) therapies." (PMID 37397251, 2023). "This points out a possible function of CSK as a tumor suppressor as well." (PMID 36578781, 2022). "CSK protein is upregulated in response to androgen withdrawal in LNCaP and LAPC4 cells strongly suggest that commonly administered androgen deprivation therapy may impose selective pressure on tumor cells to downregulate CSK levels/activity for progression to castration resistance." (PMID 26091350, 2015). "Our data also suggest that CSK low CRPCs might respond to inhibition of pathways and cellular processes set into motion by loss of ETS2 and ZFHX3 function, two tumor suppressors specifically involved in the transition to CRPC, although regimens to do so remain to be discovered." (PMID 26091350, 2015). "Low LPAR1 expression affected the proportion of tumor immune infiltrating cells (TIICs) in the tumor microenvironment (TME), which was related to the involvement of LPAR1 in pathways such as CSK and Th1/Th2." (PMID 41462160, 2025). "GSEA of Biocarta pathways identified five up-regulated pathways with FDR < 0.05 in the M3 iSubtype, which were mainly involved in immune system (CTLA4, CSK, TCR) and tumor progression (SPPA, BAD)." (PMID 34944787, 2021). "To explore whether ACK1-mediated CSK Y18 phosphorylation is a signalling event driving immunosuppression, we aimed to elucidate the effect of ACK1 inhibition on CRPC tumour growth." (PMID 36376335, 2022). "More recently, the tumour suppressive effect of Cx43 expression could be explained by the region 266–283 in the CT domain of Cx43 which is able to recruit PTEN and C-Terminal src kinase (Csk) to inhibit the oncogenic activity of c-Src." (PMID 29865195, 2018).
infection (5 papers, 2012 to 2025). The state of being infected such as from the introduction of a foreign agent such as serum, vaccine, antigenic substance or organism. "Infection with both CSK shRNA lentiviruses #1 and #2 almost completely abolished the fulvestrant-induced ERα protein degradation when examined by Western blotting." (PMID 23593342, 2013). "Furthermore, the levels of p-Src, p-p38 MAPK, p-caveolin-1 Tyr14, and dynamin 2 in ARV-infected cells were further increased in cells which were pretreated with CSK inhibitor before infection for 2 h." (PMID 37097149, 2023).
neurologic diseases (1 paper, 2022). "Being an inhibitor of Fyn, CSK might be important in the development of these neurologic diseases." (PMID 36578781, 2022).
CSK also shares sentences with these, for which no sentence is quoted: cervical cancer (3 papers); melanoma (3); squamous cell carcinoma (3); leukemia (2); lymphoma (2); AIDS (1); ankylosing spondylitis (1); Arthritis (1); Astroglioma (1); bacterial infection (1); cardiovascular diseases (1); chondrosarcoma (1); chronic periodontitis (1); colorectal tumors (1); Cryptosporidium infection (1); cutaneous squamous cell carcinoma (1); dengue (1); endometrial cancer (1); endothelial dysfunction (1); giant cell arteritis (1); glioma (1); head and neck squamous cell carcinoma (1); hematologic malignancies (1); Henoch-Schönlein purpura (1); Insulin resistance (1); ischemia (1); lens diseases (1); liver cancer (1); lobular carcinoma (1); lung adenocarcinoma (1).
A further 16 diseases each share a sentence with CSK in 1 paper.